INS (insulin)
Diseases named in the same sentence as INS in open-access papers (continued):
Sharing a sentence is not in itself a finding about the gene and the disease.
Hyperinsulinemia (continued). "Systemic administration of FGF21 improves insulin sensitivity, spares insulin secretion and ameliorates hyperinsulinemia." (PMID 23209571, 2012). "In liver cirrhosis, insulin sensitivity decreases in peripheral tissue, for which pancreatic β cells compensate through the secretion of excess insulin, inducing hyperinsulinemia." (PMID 22509183, 2012). "To verify some of the most interesting findings of the microarray study, we performed qPCR quantification of mRNAs for 8 genes, for 11 insulin-sensitive and 9 insulin-resistant women, under fasting and at the 3 h and 6 h time points of hyperinsulinemia." (PMID 22471940, 2012). "It should be noted, however, that high fasting insulin levels (hyperinsulinemia) often occur at the same time as reduced insulin secretion upon glucose stimulation, due to β-cell dysfunction." (PMID 23110768, 2012). "A fasting test again confirmed hypoglycemia and endogenous hyperinsulinism with a serum glucose values 1.6 mmol/L, serum insulin and C-peptide were 24.8 mE/L, and 1.03 nmol/L respectively." (PMID 23243524, 2012). "Ten hours after the last ingestion of food, her plasma glucose was 1.8 mmol/L, serum insulin and C-peptide were 22.8 mE/L, and 0.97 nmol/L respectively, clearly indicating endogenous hyperinsulinism." (PMID 23243524, 2012). "From 10 to 15 weeks of age, IUGR rats developed hyperinsulinemia, which suggested that insulin sensitivity of IUGR rats deteriorated with age." (PMID 22022381, 2011). "By examining changes in the fasting insulin level at various stages, it was clearly illustrated that hyperinsulinemia was induced by the high-fat diet, and impaired insulin secretion was achieved with a low-dose STZ injection." (PMID 21274451, 2011). "There is evidence that high insulin levels in bloodstream results in hyperinsulinemia in cerebrospinal fluid." (PMID 22389813, 2011). "On the other hand, others argue that insulin, especially in the context of hyperinsulinemia, increases the proliferation of endothelial and vascular smooth muscle cells and exacerbates the inflammatory response." (PMID 22093181, 2011). "Conversely, sustained, complete inhibition of IDE in all tissues, by inducing chronic hyperinsulinemia, elicits compensatory changes to insulin signaling that contribute to insulin intolerance and, hence, glucose intolerance." (PMID 21695259, 2011). "The results observed were considered to occur through hyperinsulinemia and modulation of insulin-IGF axis." (PMID 22174655, 2011). "Chronic peripheral hyperinsulinemia results in an increase of insulin in the cerebrospinal fluid (CSF) but reduced insulin signaling in brain." (PMID 22654727, 2011). "Ibanez and colleagues define hyperinsulinemia as a peak insulin of > 150 μU/mL during a 2-hr oral glucose tolerance test and/or mean serum insulin levels of > 84 μIU/mL during standard oral glucose tolerance testing." (PMID 21899727, 2011). "At normal physiological concentrations insulin exerts prevailing antiinflammatory effects, while hyperinsulinemia increases levels of oxidative stress and inflammation." (PMID 20634940, 2010). "Since cells need glucose for their survival, more insulin is produced by the pancreas resulting in hyperinsulinemia." (PMID 21234175, 2010). "Decreased insulin clearance has also been suggested as another pathway for hyperinsulinemia in liver." (PMID 20426802, 2010). "We have previously demonstrated that feeding rats diets with increased protein and reduced carbohydrates enhances muscle insulin signaling and glucose uptake, attenuates post-prandial hyperinsulinemia, and stimulates skeletal muscle protein synthesis." (PMID 20148110, 2010). "The data of Boc5 treatment on glucose homeostasis and hyperinsulinemia were suggestive of improvement in insulin sensitivity." (PMID 21151924, 2010).
Hyperinsulinemia (continued). "These rats have hyperinsulinemia and it has been reported that in muscle cells chronic insulin stimulation can activate the over expression of Glut 1 and Glut 3 by two different pathways." (PMID 21044347, 2010). "Despite normal fasting plasma glucose and insulin levels, the 2 hour plasma glucose concentration during an oral glucose tolerance test showed glucose intolerance with marked hyperinsulinemia." (PMID 21274310, 2009). "As a result, there is diminished glucose disposal, hyperglycemia, and pancreatic beta cell stimulation to produce extra insulin (hyperinsulinemia)." (PMID 20379419, 2009). "The increase in circulating free fatty acids also increases insulin secretion leading to hyperinsulinemia." (PMID 19707530, 2009). "For example, there is a group of five reference terms that are all associated with insulin ("insulin action", "insulin resistance", "insulin sensitivity", "hyperinsulinemia" and "hyperinsulinaemia")." (PMID 19575795, 2009). "Hyperinsulinemia in the Fatty Group was shown at 6 weeks of age, whereas, after 12 weeks of age, the insulin level decreased to a level similar to that in the SDT Group." (PMID 19696902, 2009). "The results indicate that leptin infusion can attenuate hepatic steatosis and hyperinsulinemia through the reduction of hepatic triglyceride synthesis and the improvement of insulin sensitivity in diet-induced lipodystrophy model mice." (PMID 18348717, 2008). "To that, we used a rat model of hyperinsulinemia with normal glycemia that allowed testing lasting effects of insulin on mitochondria." (PMID 18335029, 2008). "Even in individuals with normal blood glucose response, post-prandial INS varied more than 4-fold and the greatest post-prandial INS responses (i.e. compensatory hyperinsulinemia) had the highest TAG concentrations." (PMID 18990242, 2008). "The protocol was changed to better match peak IDV concentrations with the steady state portion of hyperinsulinemia during the insulin clamp." (PMID 18713456, 2008). "All of these models demonstrate both an enhanced glucose stimulation of insulin secretion and hyperinsulinism that persists through adulthood." (PMID 18959471, 2008). "Mice with reduced KATP channel activity also demonstrate hyperinsulinism, but mice with complete loss of KATP channels (KATP knockout mice) show an unexpected insulin undersecretory phenotype." (PMID 18959471, 2008). "Conversely, the β-cell–specific Kir6.2[AAA] dominant-negative mouse demonstrates only a ∼70% decrease in β-cell KATP channel activity, and exhibits insulin hypersecretion with hyperinsulinemia that persist through adulthood." (PMID 18959471, 2008). "As a result, whereas the wild type UCP2 inhibits insulin secretion by pancreatic beta cells, the mutated UCP2 promote insulin secretion and as such can explain the hyperinsulinism observed in these patients." (PMID 19065272, 2008). "This is accompanied by increased insulin synthesis resulting in hyperinsulinemia which is thought to be a compensatory response to reduced insulin sensitivity." (PMID 17437648, 2007). "Meanwhile, a high fasting insulin level is thought to be the initial state of hyperinsulinemia which is found frequently amongst PCOS-affected patients." (PMID 16603055, 2006). "After 4 days of treatment with either E2 or BPA, these mice developed chronic hyperinsulinemia, and their glucose and insulin tolerance tests were altered." (PMID 16393666, 2006). "When insulin is overexpressed, a chronic hyperinsulinemia manifests, as shown in transgenic mice that overexpressed the insulin gene." (PMID 16393666, 2006). "Although most people with BMI ≥ 30 have postprandial hyperinsulinemia and relatively low insulin sensitivity, there is variation in insulin sensitivity even within the obese population." (PMID 16948861, 2006).
Hyperinsulinemia (continued). "Those investigators suggested that calorie restriction resulted in decreased insulin levels, implicating hyperinsulinemia in obese ad libitum fed rats as a mechanism in increased tumor promotion." (PMID 16168107, 2005). "With overexpression of glutamine:fructose-6-phosphate amidotransferase, the key regulatory enzyme in hexosamine synthesis, the liver produces excess fatty acids, skeletal muscle becomes insulin resistant, and hyperinsulinemia results." (PMID 15723702, 2005). "Hyperinsulinemia augments androgen production in PCOS directly by augmenting LH activity through stimulation of ovarian receptors of insulin and insulin-like growth factors or indirectly, by enhancing the amplitude of serum LH pulses." (PMID 16095537, 2005). "In an attempt to keep euglycemia, insulin secretion increases and the resultant compensatory hyperinsulinemia, in obese patients, reduces the expression of the membrane insulin receptor (down regulation), which generates more resistance to the insulin action." (PMID 15963228, 2005). "A plethora of data point to insulin resistance (IR) and hyperinsulinemia as the central factor, a suggestion supported by clinical benefits of insulin sensitizers." (PMID 16095537, 2005). "ZD7114 treatment limited the hyperinsulinemia induced by the cafeteria diet, as demonstrated by the 2.3 fold decrease in plasma insulin concentrations in CAF-ZD rats compared with the CAF group." (PMID 15507149, 2004). "Measurement of insulin and glucose concentrations in plasma of fasted animals showed that CAF rats presented a marked hyperinsulinemia with a 4.6 fold increase in insulin concentration as compared to REF animals whereas the glucose level was not changed." (PMID 15507149, 2004). "This present report demonstrates that ZD7114 treatment reduced the hyperinsulinemia elicited by the cafeteria diet (by 2.3 fold), thereby suggesting an improvement of insulin sensitivity in the treated rats." (PMID 15507149, 2004). "NENs arising in these regions, including those with liver metastases, may thus be especially vulnerable to the effects of hyperinsulinemia due to their anatomical proximity to insulin-secreting β cells." (PMID 41394112, 2026). "By lowering chronic hyperinsulinemia, SGLT2is may mitigate insulin-induced cellular senescence, thereby improving metabolic flexibility and tissue function." (PMID 41189469, 2026). "This insulin-mediated CB1R stabilization provides a novel mechanistic link between hyperinsulinemia and the exacerbation of MASLD/MASH, suggesting that the hepatic insulin-ERK-CB1R axis may be a potential therapeutic target for metabolic liver diseases." (PMID 42158822, 2026). "The distinct patterns of plasma insulin kinetics were noticedbetween fasted and fed diabetic mice receiving the same casNP/insulin/C10 dosage, indicating the capability of casNP/insulin/C10 to respond to food intake and prevent hyperinsulinemia underfasting conditions." (PMID 41442621, 2026). "To confirm the induction of T2DM pathophysiology in the device, we evaluated whether the m-POs exhibited impaired insulin secretion, glucose intolerance, and hyperinsulinemia 52-54." (PMID 41328336, 2026). "By improving insulin sensitivity, metformin may break the cycle of hyperinsulinemia-driven senescence." (PMID 41189469, 2026). "The mechanisms responsible for the increase in BP include, among others, tissue resistance to insulin with secondary hyperinsulinism, excessive activation of the sympathetic nervous system, disorders in the renin–angiotensin–aldosterone system (RAA), and chronic low-intensity inflammation." (PMID 41596212, 2026). "Despite sufficient insulin or IGF-1 levels, persistent hyperinsulinemia may cause receptor desensitization, thereby blunting anabolic signaling." (PMID 41464556, 2025).
Hyperinsulinemia (continued). "Supplementation with α-LA and LTA revealed superior ability to improve glucose tolerance test and skeletal muscle glucose uptake, reduce hyperinsulinemia, and enhance body composition by increasing lean mass relative to fat, compared to gene therapy or liver-targeted insulin administration." (PMID 41004024, 2025). "This stimulates β cells to secrete insulin, leading to compensatory hyperinsulinemia." (PMID 39948335, 2025). "Postprandial hyperinsulinemia also affects cerebrospinal fluid (CSF) insulin levels." (PMID 40806659, 2025). "They proposed that peripheral hyperinsulinemia in the prediabetic situation is caused by reduced hepatic insulin clearance rather than by pancreatic insulin overproduction." (PMID 41009753, 2025). "Drug-induced acanthosis nigricans may be associated with an array of prescribed medications that may induce hyperinsulinemia such as steroids, oral contraceptives, estrogen, insulin and nicotinic acid." (PMID 38602653, 2025). "Hyperinsulinemia, which occurs in order to compensate for decreased insulin sensitivity, activates the mitogen-activated protein kinase pathway, which leads to increased mitogenic responsiveness to insulin." (PMID 39941639, 2025). "The data obtained by in vivo analyses revealed that subcutaneous injection of 5-AMQ in diet-induced obese C57Bl/6 mice caused significant weight loss, reduced adipose tissue mass, improved oral glucose tolerance and insulin sensitivity, and suppressed hyperinsulinemia." (PMID 41301471, 2025). "In people with no chronic diseases, IR could be an earlier stage with sustained compensatory hyperinsulinemia, allowing pro-tumorigenic pathways (high insulin/IGF-1, proliferation, anti-apoptosis, low-grade inflammation, oxidative stress) to act more directly." (PMID 41419984, 2025). "Metformin, by improving insulin sensitivity and reducing hyperinsulinemia, may have an indirect effect on AMH levels." (PMID 40281834, 2025). "These could reside in differences in quantities and qualities of breast milk and IF milk, exposure to hyperinsulinemia in the milk from insulin-resistant mothers, or consequences of post-deprivation catch-up growth." (PMID 40077697, 2025). "This study investigated the impact of hyperinsulinemia and high-glucose on BC cell proliferation, with particular attention to the modulation of cell signalling, proliferation, and invasiveness induced by insulin." (PMID 40806650, 2025). "IGF-1 declined (p = 0.005) in obese mares with hyperinsulinemia and normal insulin." (PMID 40901060, 2025). "The conventional method of subcutaneous insulin administration delivers insulin directly into the peripheral circulation—bypassing first-pass hepatic clearance–and thereby results in iatrogenic peripheral circulation hyperinsulinemia." (PMID 40045281, 2025). "The sustained increase in circulating insulin is known as hyperinsulinemia." (PMID 40868096, 2025). "The current gold standard for T1DM and advanced T2DM patients is to directly inject insulin into the peripheral circulation, bypassing the liver, with the risk of non-physiological hyperinsulinemia." (PMID 41471078, 2025). "Peripheral hyperinsulinemia, a consequence of subcutaneous insulin delivery, may explain these findings by directly increasing lipoprotein lipase (LPL) activity." (PMID 40755902, 2025). "Interestingly, they found that this benefit was mainly observed in patients with preoperative hyperinsulinemia suggesting insulin to be a predictor of treatment." (PMID 40423926, 2025). "Hyperinsulinemia can develop due to β-cell proliferation or heightened responsiveness of β-cells to nutrient stimulation, potentially driven by chronic overnutrition (e.g., high-sugar, high-fat diets) triggering increased postprandial insulin secretion." (PMID 40013621, 2025). "THs have been shown to induce hyperinsulinemia and stimulate insulin secretion." (PMID 40563510, 2025).
Hyperinsulinemia (continued). "Immunohistochemical studies on specimens from patients exhibiting elevated insulin levels consistently show increased AKT phosphorylation across multiple BC molecular subtypes, indicating that hyperinsulinemia is associated with enhanced AKT activation in situ." (PMID 40806650, 2025). "Additionally, hyperinsulinemia, common in obese patients, enhances tumor growth through the activation of the insulin–IGF-1 axis, particularly in colorectal, renal, prostate, and endometrial cancers." (PMID 41432903, 2025). "At hyperinsulinemia exceeding postprandial levels, glucose disposal was found either lower or similar to healthy humans, suggesting decreased or normal responsiveness to insulin, respectively." (PMID 39998445, 2025). "However, this perspective obscured the biological and iatrogenic factors contributing to weight gain in T1D, specifically hyperinsulinemia, glucose variability, and appetite dysregulation resulting from intensive insulin therapy." (PMID 41497311, 2025). "However, hyperinsulinemia’s relationship between chronic high insulin and intracellular Ca2+ homeostasis is dysregulated." (PMID 40137469, 2025). "Since insulin has been shown to have a tropic effect on erythroid maturation and differentiation in vitro, the stimulatory effect of IR-induced hyperinsulinemia was suggested to mediate this effect in vivo." (PMID 39980584, 2025). "This could be explained by the fact that in an IR state, insulin secretion is enhanced, which results in hyperinsulinemia." (PMID 40259008, 2025). "Circulating insulin levels reflect the rate of its metabolic clearance as well as the rate of its secretion, and both might contribute to hyperinsulinemia." (PMID 40013621, 2025). "In vivo hyperinsulinemia and in vitro exposure of cardiomyocytes to high glucose or insulin led to an increase in SGLT1 expression by increasing binding of the transcription factors HNF-1 and Sp1 to the SGLT1 gene (Slc5a1), and the transcript stabilizer HuR to SGLT1 mRNA." (PMID 40932483, 2025). "This indicates that vitamin D may facilitate early-phase insulin release after glucose stimulation, potentially preventing the compensatory hyperinsulinemia characteristic of PCOS." (PMID 40868057, 2025). "In such a scenario, an elevation in androgens could further escalate hyperinsulinemia by impairing insulin clearance and inducing insulin hypersecretion." (PMID 40013621, 2025). "Many studies were done on hyperinsulinemia in blood vessels, particularly in cultured vascular endothelial cells and VSMCs of different animal species, which are affected by high circulating insulin." (PMID 40137469, 2025). "Collectively, this suggests that diminished insulin clearance may be a fundamental feature that perpetuates hyperinsulinemia in some PCOS patients." (PMID 40013621, 2025). "The finding of increased GIP and insulin in the plasma of rotenone-treated rats suggests that the elevated level of GIP might have been responsible for the upregulation of insulin called hyperinsulinemia." (PMID 39851552, 2025). "In addition, the KATP channels in the dorsal motor nucleus of the vagal nerve, pancreatic β-cells, and adipocytes are activated, reducing hyperinsulinemia and body fat, directly or indirectly leading to improved insulin and leptin resistance and satiety." (PMID 40136445, 2025). "In obese mice, the administration of a GPR120-selective agonist has shown promising effects in enhancing glucose tolerance, improving insulin sensitivity, reducing hyperinsulinemia, and alleviating hepatic steatosis, all likely due to the increased insulin secretion." (PMID 40001594, 2025). "While insulin can significantly increase muscle protein synthesis in young adults when muscle amino acid availability is increased, healthy, nondiabetic older humans exhibit resistance, requiring supraphysiological hyperinsulinemia for stimulation." (PMID 39544124, 2025).